TRIM28 (tripartite motif containing 28)
Diseases named in the same sentence as TRIM28 in open-access papers (continued):
Sharing a sentence is not in itself a finding about the gene and the disease.
tumor (continued). "In this study, we also found that the regulatory role of TRIM28 on the expression of MAGEC2 protein in tumor cells is proteasome-dependent, which may be related with the E3 ubiquitin ligase activity of TRIM28." (PMID 30309319, 2018). "Targeted Sanger sequencing of all TRIM28 exons of this tumour (SCTBN 88) did not identify any mutations and exon 1 was unmethylated." (PMID 29912901, 2018). "The growth kinetics of MDA-MB-231 and MCF-7 xenografts suggested that TRIM28 depletion led to the inhibition of tumor growth in MDA-MB-231 cells (p = 1E-04), which have a high percentage of CD44+/CD24−/low cells, but not in MCF-7, which have a very low number of CD44+/CD24−/low cells." (PMID 27845900, 2017). "Next, we decided to elucidate the role of TRIM28 protein in regulation of tumor growth in vivo." (PMID 27845900, 2017). "TRIM28-mediated regulation of tumor growth in vivo differs from in vitro observations." (PMID 27845900, 2017). "Importantly, increased expression of TRIM28 associated with decreased expression of FBP1 and tumor node metastasis stage of HCC." (PMID 28394358, 2017). "However, double knockdown of FBP1 and TRIM28 abolished TRIM28 knockdown-induced inhibition of SK-Hep-1 tumor growth in mice." (PMID 28394358, 2017). "To further verify whether TRIM28-dependent inhibition of tumor growth and TRIM28-related downregulation of pluripotency markers expression are associated with a reduction in the CSC subpopulation, we performed a limiting dilution transplantation assay." (PMID 27845900, 2017). "The tumor suppressive role of TRIM28 is also evident, but mostly in early stages of cancer." (PMID 27412325, 2016). "We hypothesize that Trim28, through regulation of multiple alternative pathways may have both tumor suppressing and oncogenic activities much like the TGF-β signaling pathway is known to play a complex role tumorigenesis." (PMID 24983967, 2014). "However, Trim28 deletion also led to excessive deposition of tumor extracellular matrix (ECM)." (PMID 41508128, 2026). "Thus, the simultaneous activation of NFκB and JAK/STAT signaling in TRIM28-deficient cells provides a plausible mechanistic link to enhanced expression of CD24/CD47, suggesting that TRIM28 modulates tumor–immune interactions through coordinated regulation of cytokine and adhesion pathways." (PMID 41303350, 2025). "TRIM28 may inhibit the sensitivity of tumor cells to chemotherapy." (PMID 39100077, 2024). "Overall, these studies indicate that TRIM28 may be a potential tumor promoter in PCa." (PMID 39100077, 2024). "However, the role and mechanism of TRIM28 in tumor immunity still needs to be further explored." (PMID 36756159, 2023). "Notably, TRIM28 mRNA levels were substantially higher in NSCLC tissues than in non-tumor tissues." (PMID 37865804, 2023). "Based on our observations that TRIM28 expression is strongly associated with MDSC infiltration in NSCLC, we hypothesized that TRIM28 promotes the chemotactic recruitment of MDSCs into the tumor microenvironment." (PMID 37865804, 2023). "The rim regions, enriched with invading cells, were mostly expressing PN and MIX GB genotypes, but support the notion that TRIM28-eriched MES GB cells may have been detached from the tumour, representing the more aggressive MES-GSCs that seed novel GB islets in the brain." (PMID 34500575, 2021). "Furthermore, the level of RIPK3 and TRIM28 in the tumor could be an indicator for the applicability of ICD-based immunotherapy in the selection for therapeutic approaches." (PMID 34419074, 2021). "However, in a murine model, TRIM28 was reported to be a tumour suppressor in HCC." (PMID 32731534, 2020). "Neither of the TRIM28-mutated tumours (37T and W117) had AMER1 mutations." (PMID 29912901, 2018). "In comparison, 12 of 16 other tumours without TRIM28 variants showed extensive copy number change." (PMID 29912901, 2018). "In addition, patients with elevated expression of TRIM28 suffered shorter tumor-specific survival." (PMID 29127420, 2017).
tumor (continued). "Therefore, TRIM28 is essential for non-tumor cells to maintain their unchanged phenotype." (PMID 28851455, 2017). "We focused on the initial response to Trim28 deletion at 1 month after tumor induction, as YFP-lineage marked tumor cells in late-stage NPp53T tumors display sarcomatoid features, with malignant cells invading the stroma." (PMID 41508128, 2026). "In summary, we identify a TRIM28-PPARG SUMO-ubiquitin crosstalk axis that drives metabolic remodeling and tumor growth in BLCA, highlighting TRIM28-mediated PPARG SUMOylation as a potential therapeutic target for metabolic intervention." (PMID 41974657, 2026). "While TRIM28 repression of ERVs has been examined in several cell types including ES cells and neural progenitor cells, our study examined ERV expression in a tumor context." (PMID 41508128, 2026). "The presence of accessible cysteines in TRIM28 and EZH2 further highlights the potential of this strategy in disrupting their interaction and reactivating silenced genes involved in tumor suppression." (PMID 41504013, 2026). "In the context of tumor development, MAGE proteins interact with the transcriptional master regulator and E3 ubiquitin ligase KAP1 (TRIM28), thereby inducing the degradation of tumor suppressor proteins." (PMID 40112032, 2025). "In tumour cells, the expression levels of MAGEC2 depend on the expression levels of TRIM28, as a significant decrease in MAGE28 levels was observed in TRIM28 depleted cells." (PMID 39990257, 2025). "It is worth noting that TRIM28 reportedly exhibits a dual function in CRC, where it promotes tumor cell proliferation while concurrently inhibiting epithelial–mesenchymal transition (EMT) via epigenetic regulation." (PMID 41194971, 2025). "Our experiments confirmed that DDX21 and TRIM28 are highly expressed in CRC and demonstrated that downregulation of either gene significantly inhibits tumor cell proliferation and migration." (PMID 41194971, 2025). "In GC cells, TRIM28 significantly increases PD-L1 expression by activating the TBK1-mTOR pathway, suppressing T-cell activation, and promoting tumor progression." (PMID 40140647, 2025). "Evident by comparison to their cognate normal tissue analogs, discernible upregulation was registered across a slew of tumor tissues for PPIA, TRAF2, TRIM28, and HGS." (PMID 38460947, 2024). "Second, in terms of chemoresistance, WDR4 can increase the translation of TRIM28, thereby enhancing the stemness of tumor stem cells, promoting HCC resistance to Lenvatinib and tumor progression." (PMID 39850560, 2024). "TRIM28 promotes epithelial-to-mesenchymal transition (EMT) and metastasis of tumor cells through stabilization of Twist-related protein 1 (TWIST1) and activation of Wnt/β-catenin signaling." (PMID 39532800, 2024). "XAF1 exerts apoptosis-promoting effect more strongly in TRIM28+/+ versus XAF1−/− tumor cells and suppresses tumor cell growth, migration, invasion, and epithelial-to-mesenchymal transition and xenograft tumor growth in a highly TRIM28-dependent fashion." (PMID 39532800, 2024). "In melanoma cancer cells, the MAGE protein upregulates ATM-dependent pS824-TRIM28 by promoting the binding of TRIM28 to ATM, thereby enhancing DDR and promoting tumor progression." (PMID 39100077, 2024). "The phosphorylation of TRIM28 results in chromatin relaxation, enhancing DNA repair machinery access (including BRCA1 and 53BP1) to the damage site, thereby promoting tumor progression." (PMID 39160596, 2024). "In NSCLC cells, TRIM28 promotes TGF-β-induced EMT by silencing E-cadherin expression, thereby promoting tumor cell migration and invasion." (PMID 39100077, 2024).
tumor (continued). "Collectively, we found that XAF1 destabilizes TRIM28 and thereby antagonizes its oncogenic activity to suppress tumor cell malignancy while TRIM28 destabilizes XAF1 to protect tumor cells from apoptotic stresses." (PMID 39532800, 2024). "Both TRIM28+/+ and TRIM28−/− tumors were exposed to doxycycline (Dox) for XAF1 induction at day 36 after inoculation and tumor growth was compared." (PMID 39532800, 2024). "Because OC is primarily a tumor of epithelial origin, the expression of TRIM proteins was analyzed in epithelial cells, and the eight most highly expressed genes (TRIM28, TRIM27, TRIM33, TRIM38, TRIM47, TRIM56, TRIM8, and TRIM24) were determined." (PMID 38881325, 2024). "TRIM28 overexpression in CMT-167 tumors led to an upregulation of CXCL1 levels in tumor tissue, tumor lysates, and serum." (PMID 37865804, 2023). "In this study, we find higher TRIM28 level correlates with better RCC patient survival and TRIM28 suppresses RCC cell proliferation and tumor growth." (PMID 36935008, 2023). "Moreover, RIPK3-phosphorylated TRIM28 could upregulate NF-κB in tumor cells, leading to elevated immunostimulatory cytokine such as GM-CSF expression, thereby contributing to robust cytotoxic anti-tumor immunity." (PMID 37375731, 2023). "In NSCLC cells, knockdown of TRIM28 can block TGF-β-induced EMT, thereby decreasing the tumor cell migration and invasion." (PMID 36756159, 2023). "Our study demonstrated that TRIM28 exhibits high expression in NSCLC tumor tissues and is positively correlated with the infiltration of MDSCs in the tumor microenvironment." (PMID 37865804, 2023). "TRIM28 knockdown increased responsiveness to anti-PD-1 therapy in immunocompetent mice, characterized by increased CD8+T tumor-infiltrating lymphocytes and decreased MDSCs." (PMID 37865804, 2023). "With respect to cancer, KZNF proteins, as well as TRIM28 and SETDB1, have been shown to exert pleiotropic roles as oncogenes or tumor suppressors in different tumor types." (PMID 35162997, 2022). "It indicated that TRIM28 was an oncogene, while TRIM58 is more likely to be a tumor suppressor gene." (PMID 36461099, 2022). "The results show that KRT8, PSMD2, TRIM28, and UBE2V2 are significantly overexpressed in tumor tissues, while the expression level of FBXO9, MYLIP, and RNF180 is significantly reduced in LUAD (p < 0.05)." (PMID 35711913, 2022). "However, the expression of TRIM28 had a significant negative association with the tumor-infiltrating immune cell populations, consistent with our hypothesis." (PMID 34419074, 2021). "TRIM28 also regulates the epithelial-mesenchymal transition (EMT) pathway and enable tumor cells to acquire mesenchymal phenotype and become more aggressive." (PMID 34330324, 2021). "Next, to examine TRIM28 protein levels in primary patient tissues and to evaluate its correlation with TRIM24, we performed immunohistochemistry (IHC) in human PCa tumor progression tissue microarrays (TMA)." (PMID 30479348, 2018). "To verify the manipulation of these proteins at the endpoint, we performed IHC in tumor tissue sections and found that both TRIM28 and TRIM24 protein stained predominantly in the nuclei and their staining intensities were decreased in TRIM28-knockdown tumors." (PMID 30479348, 2018).
tumor (continued). "Further, KI-67 staining was reduced in TRIM28-knockdown tumors and was partially rescued in TRIM24-reexpressing tumors, being concordant with their respective tumor growth rates." (PMID 30479348, 2018). "We found that TRIM28-knockdown cells showed retarded xenograft tumor growth and ectopic re-expression of TRIM24 in these cells partially rescued xenograft tumor growth." (PMID 30479348, 2018). "To examine the tumorigenic roles of TRIM28 in vivo, we inoculated control, TRIM28-knockdown, or TRIM28-knockdown and TRIM24-re-expressing C4-2B cells into SCID mice and monitored xenograft tumor growth." (PMID 30479348, 2018). "Our data revealed that TRIM28-KD significantly reduced xenograft tumor size, which can be rescued by TRIM28-WT but not TRIM28-S473A." (PMID 40519166, 2025). "Interestingly, parts of genes, such as TSPAN1 and TRIM28, had higher accessibility of enhancer region in GBM compared to LGG and were significantly upregulated in tumour tissue than normal brain tissue." (PMID 38685685, 2024). "Intriguingly, TRIM28 destabilizes XAF1 through K48-linked polyubiquitination and proteasomal degradation to protect tumor cells from apoptotic stress, indicating its role as an intrinsic antagonist against XAF1 and the antagonistic interplay of XAF1 and TRIM28." (PMID 39532800, 2024). "Taken together, tumor-infiltrating immune cells, especially B cells, may serve influential roles in the clinical outcomes of patients with HCC with different levels of TRIM28 expression." (PMID 37870748, 2023). "Because of the importance of TRIM28 in tumors, TIRM28 may be a candidate target for anti-tumor therapy and play an important role in tumor diagnosis and treatment in the future." (PMID 36756159, 2023). "TRIM28 plays a critical role in maintaining the intrinsic phenotype of non-tumor cells without malignant transformation." (PMID 36756159, 2023). "Specific TRIM28 inhibitors could be further developed and validated in combination with anti-CTLA4 therapy to suppress tumor growth efficiently." (PMID 37357254, 2023). "The immunohistochemistry (IHC) images also showed that TRIM28 was more expressed in tumor tissues than in nontumor tissues." (PMID 36238495, 2022). "In GSE63898, the expression of TRIM28 in nontumor tissues was notably lower than that in tumor tissues." (PMID 36238495, 2022). "Meanwhile, TRIM28 expression was not significantly related to age, tumor size, vascular or nerve invasion condition, histologic grade, ER, PR, HER-2, and Ki67 expressions." (PMID 33817325, 2021). "We demonstrated that regardless of the tumor type, only high TRIM28 expression consequently corresponds to higher tumor stemness, while high TRIM66 expression is negatively associated with tumor stemness." (PMID 33810347, 2021). "Studies have shown, for example, that TRIM28 knockdown may be effective against NSCLC, and the knockdown of TRIM28 expression by lenti-siRNA/TRIM28 may inhibit tumor growth and induce cell apoptosis in vivo." (PMID 30484263, 2019). "In line with this, DFTD tumor cells expressed higher levels of TRIM28 compared with fibroblasts, and blockade of either ERBB signaling or STAT3 led to reduced transcription of TRIM28." (PMID 30645971, 2019). "Furthermore, low levels of stromal TRIM28 correlated with elevated MDM2 levels in tumor epithelium (p = 0.01) and COX-2 levels in tumor stroma (p = 0.002)." (PMID 29631612, 2018). "The expression level of MAGEC2 protein was significantly reduced when TRIM28 was depleted in tumor cells, and no changes were observed in MAGEC2 mRNA level." (PMID 30309319, 2018).
tumor (continued). "Since TRIM28 can regulate several hundred different genes in its role as a transcriptional co-repressor, we investigated its role within LCM-enriched stromal and epithelial compartments derived from patient tumor tissue." (PMID 29631612, 2018). "Expression levels of TRIM28 and MAGEC2 are detected in different tumor cell lines." (PMID 30309319, 2018). "The expression patterns of AMER1 and TRIM28 mutant tumours did not, however, cluster together, nor did they show similar histological features, suggesting that these two proteins contribute to different tumorigenic pathways." (PMID 29912901, 2018). "All three tumours had a complete absence of TRIM28 protein in neoplastic cells, although non-tumour-derived endothelial cells and residual non-neoplastic kidney epithelial structures (K) showed positivity." (PMID 29912901, 2018). "Following unsupervised clustering analysis of genome-wide gene expression the TRIM28 and AMER1-mutated tumours did not cluster together." (PMID 29912901, 2018). "The expression levels of the five most down-regulated and five most up-regulated genes in the S1 compared to S2-S5 subgroups were examined in the TRIM28-mutant and non-mutant tumours." (PMID 29912901, 2018). "Tumour SCTBN 88, which also showed monomorphic epithelial histology but no TRIM28 mutations, exhibited a normal pattern of TRIM28 expression by immunohistochemistry." (PMID 29912901, 2018). "We dissected out all xenograft tumors at the endpoint and found significantly (T-test, P = 0.001) reduced endpoint tumor weight without affecting overall mice body weight in the TRIM28-knockdown group." (PMID 30479348, 2018). "Importantly, the expression of TRIM28 was closely correlated with tumor size, tumor stage and 5-year overall survival in HCC patients, showing remarkably shorter survival rate in patients with TRIM28 overexpression." (PMID 28851455, 2017). "MAGE-C2 increases co-precipitation of TRIM28 with ATM and binding of MAGE-C2 to TRIM28 is necessary for increased TRIM28-Ser824 phosphorylation, resulting in enhanced DNA damage repair and, consequently, in promoting tumor progression." (PMID 28851455, 2017). "This upregulation may represent a compensatory response to maintain immune suppression in the absence of TRIM28, particularly in aggressive tumor subtypes exhibiting CSCs phenotypes." (PMID 41303350, 2025). "In murine models of pancreatic necrosis, TRIM28 was shown to regulate CD47 expression through modulation of miR-133a, whereby TRIM28 depletion led to increased miR-133a levels, suppressed CD47 expression, and enhanced macrophage-mediated clearance of tumor cells." (PMID 41303350, 2025). "Interestingly, we found that XAF1 is a novel substrate of TRIM28 and that EGF-induced TRIM28 protects tumor cells from etoposide-induced apoptosis more significantly in XAF1+/+ versus XAF1−/− cells, indicating that TRIM28 exerts anti-apoptotic effect in a highly XAF1-dependent fashion." (PMID 39532800, 2024). "Consequently, we hypothesized that lnc-TRIM28-14, CD93 and COL4A1 could regulate GCPM and could be novel tumor markers and potential therapeutic targets for GCPM." (PMID 36690975, 2023). "Therefore, the TRIM28 positive association and TRIM66 negative association with tumor stemness is a common phenomenon across solid tumors." (PMID 33810347, 2021). "However, further studies are needed to define the exact mechanism(s) of TRIM28-mediated stemness acquisition and to verify its universality regardless of tumor type." (PMID 33810347, 2021). "TRIM28 levels had strong negative associations with the infiltrating levels of CD8+ T cells in 24 tumor types, CD4+ T cells in 14 tumor types, macrophages in 25 tumor types, neutrophils in 27 tumor types and dendritic cells in 24 tumor types." (PMID 33091876, 2020). "Thus, we proposed that TRIM28 may negatively regulate the TIME and thereby promote tumor development and progression." (PMID 33091876, 2020).